CLU (clusterin)
Diseases named in the same sentence as CLU in open-access papers (continued):
Sharing a sentence is not in itself a finding about the gene and the disease.
tumor (continued). "GEPIA analysis revealed consistent results that CLU was highly expressed in tumor samples than normal samples in LGG." (PMID 37686218, 2023). "Increases the expression of NCOA3 and CLU, which subsequently decreases metastasis and tumor growth." (PMID 36207986, 2023). "In clear cell renal carcinoma (CCRC), the overexpression of CLU regulates tumor progression and metastasis of human CRCC cells via modulation of ERK1/2 signaling and MMP-9 expression." (PMID 37685987, 2023). "In the protein level, the gene expression of HSP90AA1, NFKB2, PTK2 was upregulated in tumor tissues, and CLU, JAK2, MAP3K5, and S100B were downregulated in the normal tissues." (PMID 36323529, 2023). "CLU functions as a molecular chaperone in various physiological processes that contribute to carcinogenesis and tumor formation, including apoptotic cell death, cell cycle control, DNA repair, cell adhesion, tissue remodeling, and lipid transport." (PMID 36685863, 2022). "This study further assessed the expression of CLU mRNA and miR-1276 in xenograft tumor using qRT-PCR." (PMID 35687899, 2022). "In the cell subsets of normal samples, FN1 and ANXA1 were high expressed in tumor cells and low expressed in myeloid cell and fibroblast; CLU was low expressed in tumor cells and high expressed in myeloid cell and fibroblast." (PMID 35359404, 2022). "While the expression of CLU in the cytosol of neoplastic cells inhibits their apoptosis, promoting tumor growth and the development of resistance to chemotherapy, nCLU shows proapoptotic properties." (PMID 36071866, 2022). "Our research also depicted a significant increase in the methylation level of CLU in PRAD tissues compared to that in non-tumor tissues." (PMID 36685863, 2022). "ITGAM was higher expressed in tumor tissues compared with normal tissues, while CLU was higher expressed in normal tissues." (PMID 35291954, 2022). "Matched with sh-NC group, pronounced reduced CLU mRNA expression and elevated miR-1276 expression was found in xenograft tumor of sh-NC + cisplatin group and sh-circ_0063804 group (P < 0.01)." (PMID 35687899, 2022). "Proteins that have an anti-apoptotic effect on tumor cells or mediate adaptation to hypoxia were detected: clusterin, CD5L, HYOU1, prosaposin, and hepatocyte growth factor activator." (PMID 35659255, 2022). "Clusterin was downregulated in tumor tissues using three datasets of tongue squamous carcinoma from the Gene Expression Omnibus." (PMID 36685863, 2022). "Herein, GEPIA2 was used to find a correlation between CLU expression and tumor prognosis in the TCGA database." (PMID 36685863, 2022). "Matched with sh-circ_0063804 group, prominently lower CLU mRNA expression and higher miR-1276 expression was displayed in xenograft tumor of sh-circ_0063804 + cisplatin group (P < 0.05 or P < 0.01)." (PMID 35687899, 2022). "According to the ITGAM (Integrin alpha M chain) and CLU (Clusterin) were differentially expressed in serum exosomes among different groups as well as tumor tissues and adjacent tissues." (PMID 35291954, 2022). "miRNA-21 overexpression leads to CLU downregulation, which sequentially stimulates tumor cell growth." (PMID 36685863, 2022). "In clinical samples of OC cases, CLU expression level was dramatically higher in tumor tissues than that in matched adjacent normal tissues (P < 0.0001)." (PMID 35687899, 2022). "Subsequent immunohistochemical analysis revealed the CLU expression, which enabled researchers to observe its presence both in the cytoplasm of tumor cells and in the apical parts of the cells of healthy tissues." (PMID 36071866, 2022). "Further systemic structural and biochemical studies are required for insight into the significance of the site-specific glycosylation status in the anti-tumour and immunosuppressive effect of clusterin on various cancer cells." (PMID 35975084, 2022). "It was revealed that CLU expression in recurrent resistant OC tissues was much higher than that in primary tumor tissues." (PMID 35687899, 2022).
tumor (continued). "Knowledge of the mechanism of metastasis formation induced by increased expression of clusterin has been used to create new anticancer therapies aimed at metastasis formation inhibition and tumor growth blockage." (PMID 36071866, 2022). "High CLU expression is also related to tumor invasiveness as well as metastasis formation, especially within the EMT mechanism." (PMID 36071866, 2022). "There is also evidence that CLU inhibition at late stages of tumor evolution can have beneficial effects in therapy, whereas at early stages increased levels of CLU likely suppress tumorigenesis." (PMID 33744871, 2021). "More than 80% collected TNBC tumor samples show to be CLU positive (CLU+), suggesting CLU+ TNBC represents the most common TNBC type." (PMID 33643800, 2021). "MEG3 (non-coding RNA maternally expressed gene) functions as a tumor suppressor in CRC by regulating the activity of clusterin, which is stimulated by the binding of vitamin D receptor to its promoter." (PMID 34218809, 2021). "In this study, we defined PRKD3 as a key regulator of CLU via inhibiting lysosomal degradation of CLU to promote TNBC tumor growth." (PMID 33643800, 2021). "Differently, under the selective pressure of cytotoxic therapies and altered signal transduction, CLU is over-expressed by resistant cells and favors the onset of a permissive tumor microenvironment." (PMID 34360868, 2021). "In TNBC samples, more than 80% (81%) and about 80% (77.2%) TNBC tumor samples are CLU+ and PRKD3+, respectively." (PMID 33643800, 2021). "In this context, the abrogation of CLU expression at early stages of carcinogenesis would fail to dampen NF-κB activity resulting in the generation of a TME conducive to the process of tumor invasion." (PMID 34360868, 2021). "Clusterin is a multifunctional, secreted chaperone involved in several basic biological events, including cell death, tumor progression and neurodegeneration." (PMID 34924950, 2021). "The expression regulation of clusterin different forms is under control of the tumor–microenvironment interactions providing local cancer growth, invasion, and metastases." (PMID 33805203, 2021). "CLU protein is a secreted chaperone which has been previously suggested to be involved in apoptosis and tumour progression." (PMID 34767591, 2021). "The apparent contradictory tumor limiting and promoting functions of CLU represents instead the two sides of the same coin, which are consistent with a cytoprotective role exerted by the protein, both under normal and pathological conditions." (PMID 34360868, 2021). "Clusterin (CLU) is a secreted chaperone protein involved in several basic biological events, such as cell death, tumor progression, and neurodegenerative disorders." (PMID 34194490, 2021). "Here, protein kinase D3 (PRKD3) is defined to be a key regulator of CLU in promoting TNBC tumor growth." (PMID 33643800, 2021). "Through an extensive co-expression network analysis, we defined the core transcriptional and epigenetic regulators for each subgroup, and identified CLU as a novel tumor suppressor from the downstream target genes of these core regulators in LUAD." (PMID 34001209, 2021). "We further show that CLU is regulated by 3 group I-specific core regulators and works as a novel tumor suppressor in LUAD." (PMID 34001209, 2021). "In a functional screening of the TSGs using CRISPR/Cas9 knockout platform in KrasG12D-based GEMM, we have previously identified CLU as an important tumor suppressor." (PMID 34001209, 2021). "The clusterin (apolipoprotein J) exhibits pro-tumorigenic, and anti-apoptotic activities and plays an important role in tumor invasiveness." (PMID 32533048, 2020). "Currently, clusterin is attracting scientific attention in the context of neoplasia mechanisms as well." (PMID 31940868, 2020).
tumor (continued). "We compared CLU expression in tumor cells from different samples and found that CLU expression was highest in tumor cells from the GSM3516671 sample, which received cisplatin +vinorelbine and associated with chemotherapeutic resistance." (PMID 33170151, 2020). "The study on incidence of tumor and development of carcinoma found that some DEPs indirectly inhibited the occurrence and development of MF, including CLU, GNAS, FZR1, and PKM." (PMID 33299887, 2020). "This is further emphasized by the reactivation of the CLU gene by all the G9a inhibitors shown in our studies, as it is a NB tumor suppressor gene known to be regulated by EZH2 and MYCN." (PMID 32537432, 2020). "Overexpression of CLU has been correlated with increased tumor aggressiveness, chemotherapy and radiotherapy resistance, and poor prognosis." (PMID 33054843, 2020). "MYCN associates with EZH2, a methyltransferase and a member of the polycomb repressor complex 2 (PRC2) to repress the NB tumor suppressor gene CLU through a bivalent modification of the chromatin at the CLU promoter." (PMID 33628735, 2020). "Statistical analyses showed that CLU deletion significantly increased mutant Kras-driven lung tumor numbers, tumor size and amount of stage 4 tumors." (PMID 33052230, 2020). "We found that expression of CLU significantly suppressed growth of xenograft tumor derived from H460-tet-CLU." (PMID 33052230, 2020). "It is worth noting that dual targeting of HSP90 and HSP27 or HSP90 and clusterin, which are also molecular chaperones, has been adapted as an effective anti-tumor treatment strategy as will be explained in the following sections." (PMID 31426412, 2019). "As the major isoform, secretory apolipoprotein J (s)CLU has been extensively investigated in the context of tumor diagnosis and prognosis owing to its anti-apoptotic function." (PMID 31117872, 2019). "A variety of studies have shown the important role of clusterin in regulating cancer cell apoptosis, tumorigenesis, and tumor progression." (PMID 28954633, 2017). "In SRCs tumors, we observed by immunohistochemistry apparently stronger expression of CLU protein in extracellular matrix than in tumor cells." (PMID 28902909, 2017). "A role for Clusterin in tumor cell senescence has been reported (reviewed in34), however its role in senescence in other cell types is less clear." (PMID 29133960, 2017). "The PhKh1 primary tumor cells resistant to ATO overexpressed transcripts coding for the molecular chaperones CLU and ANXA1." (PMID 29371980, 2017). "For instance, Clusterin and Twist expression has been related with tumor aggressiveness, tumor recurrence, and poor prognosis." (PMID 26951092, 2016). "CLU highly expresses in various human tumors, and its expression is often correlated with tumor metastasis and poor prognosis." (PMID 26716898, 2016). "In summary, we present preclinical evidence demonstrating that CLU‐KD significantly augments the anti‐tumor activity of cabazitaxel in a mCRPC model." (PMID 27198502, 2016). "The hypoxia-related markers CA-9 and clusterin significantly increased following treatment with cabozantinib, suggesting modulation of tumour hypoxia or the response thereto in the presence of cabozantinib." (PMID 26762579, 2016). "CLU is a chaperone ubiquitously expressed and involved in several physiological processes, but also in tumour growth and carcinogenesis." (PMID 25884309, 2015). "Increased CLU expression in tumour biopsies correlated with inhibition of apoptosis and tumour cell survival." (PMID 25884309, 2015). "Levels of CLU protein in tumor tissues were classified as high expression (score ++ and +++) in 120 cases (120/198, 60.6%) and low expression (score +) or not stained (score −) in 78 cases (78/198, 39.4%)." (PMID 25609201, 2015). "The clusterin expression was up-regulated in all these cells, and the level of expression was closely related to the tumorigenesis of the tumor." (PMID 26293319, 2015).
tumor (continued). "Multivariate Cox regression analysis indicated CLU expression was an independent prognostic factors for postoperative outcome (P < 0.001) and tumor recurrence (P = 0.014) in HCC patients." (PMID 25609201, 2015). "The screening analysis by Proteome Profiler showed distinctly altered expression of sE-cadherin, E-selectin, MMP2, MMP9, TIMP1, TIMP2, Galectin and Clusterin in the serum of tumor patients compared to controls." (PMID 25967040, 2015). "CLU is ubiquitously expressed but at variable levels depending on many severe physiological disturbances, including tumor formation." (PMID 25138053, 2014). "ZOL significantly increased CLU mRNA level in a dose-dependent manner depending of the tumor cell lines." (PMID 25138053, 2014). "Similar effects were also observed when OGX-011 was combined with paclitaxel chemotherapy; repression on CLU expression further delayed tumour growth and prolonged survival rate compared with control oligonucleotides." (PMID 25503391, 2014). "Our study defines a novel adaptor protein function of CLU during autophagy activation to support tumour cell survival under cancer treatment stresses." (PMID 25503391, 2014). "Elevated levels of clusterin (CLU), a stress-induced and secreted cytoprotective chaperone, are associated with advanced tumor stage, metastasis, treatment resistance, and adverse outcome in several cancers." (PMID 24156019, 2013). "Knockdown of CLU expression in HCCLM3 cells inhibited GRP78 expression in tumor tissues, accompanied with increased number of apoptotic cancer cells." (PMID 23457489, 2013). "Similar to the results obtained by in vitro experiments, knockdown of CLU in HCCLM3 cells inhibited GRP78 expression in tumor tissues, accompanied with increased number of apoptotic cancer cells." (PMID 23457489, 2013). "Clusterin has a well-documented anti-apoptotic effect, which is of clinical importance in enhancing the resistance of tumor cells to a large variety of pro-apoptotic stimuli." (PMID 22545109, 2012). "Clusterin is known to be expressed in many human neoplasms, and is believed to participate in the regeneration, migration, and anti-apoptosis of tumor cells." (PMID 22799602, 2012). "Changes in tumor volume in mice treated with MM control ODN or AS clusterin ODN alone was similar to that of untreated mice." (PMID 21609464, 2011). "BxPC-3 tumor growth was significantly inhibited by treatment with combined AS clusterin ODN and gmcitabine therapy." (PMID 21609464, 2011). "The nuclear anti-apoptotic form of clusterin is induced in late stage cancers following chemotherapy, hormonal ablation or radiotherapy, thus protecting tumor cells undergoing damaging stress." (PMID 21464964, 2011). "Clusterin is a cytoprotective chaperone protein involved in numerous physiological processes, carcinogenesis, tumor growth and tissue remodelling." (PMID 22185350, 2011). "It has been reported that CLU expression tends to increase during cellular transformation and tumor progression." (PMID 24212778, 2011). "Levels of clusterin was increased in tumor samples in comparison to matched backgrounds tissues (P = 0.0136)." (PMID 21609464, 2011). "Pathological or engineered over-expression of clusterin in various cell types confers resistance to the induction of apoptosis by several cytokines including TGFbeta, and TNFalpha and promotes tumor progression in the prostate." (PMID 20307318, 2010). "Clusterin (CLU), also more expressed in tumours from survivors in our previous studies, seems to have divergent functions in cells." (PMID 19775429, 2009). "Phase I of the clinical trials of asON OXG-011 at the dose of 640 mg reduced clusterin levels in human tumor tissue." (PMID 22649602, 2009). "Data concerning the possible involvement of CLU in transformation and tumour growth are still unclear or contradictory in the literature." (PMID 18974881, 2008).
tumor (continued). "Positive cytoplasmic staining of clusterin (CLU) was present on both tumor and normal cells in lung, breast, and ovary tissue." (PMID 17989776, 2007). "Further study of the clusterin-resistant PC-3 cells and a comparison to wild type should provide further evidence of the molecular basis of tumour resistance to apoptosis induction." (PMID 15494717, 2004). "Despite the involvement in a variety of pathologies, the role of clusterin in tumour progression and malignancy remains most controversial." (PMID 15494717, 2004). "In recent years, liquid biopsy has emerged as a novel approach for non-invasive and dynamic molecular tumor monitoring by detecting biomarkers such as circulating tumor cells (CTCs), extracellular vesicles (EVs), circulating tumor DNA (ctDNA) and clusterin (CLU)." (PMID 42123365, 2026). "Single-cell analysis of the stem cell population from ApcMin/+ tumor-bearing epithelium and WT irradiated intestine showed that both contained a population of stem cells (SSCreg) enriched in fetal/regenerative markers like Clusterin (Clu)." (PMID 40180576, 2025). "Where all genes, except for MAOA,CLU, and SIK2, were associated with poor tumour prognosis." (PMID 40028162, 2025). "CLU overexpression promoted tumor growth, which was significantly inhibited by BCL2L1 knockdown." (PMID 40606578, 2025). "It is plausible that inducing senescence by silencing CLU, in combination with senolytics, could help eliminate of tumor recurrence." (PMID 39627493, 2025). "Unlike conventional treatments that focus on killing rapidly dividing cells, CLU silencing could potentially restore tumor cells to a more vulnerable state, making them more susceptible to other therapies and reducing the likelihood of relapse." (PMID 40573993, 2025). "Targeting the overexpression of CLU in various cancers has the potential for tumor suppression." (PMID 39253532, 2024). "It is clear now that upregulation of CLU in various cancer cells plays a role in tumor progression." (PMID 39253532, 2024). "Interestingly, a correlation between the RevSC and TGFβ signalling (a key regulator of CLU expression) has been observed by several groups, with upregulated TGFβ pathway activation in RevSC-enriched tumours." (PMID 38319453, 2024). "On the other hand, intestinal epithelial Caco-2 cells exposed to IL-6 are reported to induce a substantial increase in secretory clusterin production, which promotes tumor cell survival, in addition to interfering with Bax-mediated cell death by suppressing the apoptosis-promoting function of Bax." (PMID 39451248, 2024). "Taken together, the results summarized above indicate that clusterin is protective against apoptosis generated by different stimuli, consistent with an increasing amount of data indicating that higher clusterin expression in tumor cells is protective against the death of cells via apoptosis." (PMID 39449522, 2024). "To date, several findings have established the tumor suppressive function of CLU in cancer cells." (PMID 37239129, 2023). "In support of this hypothesis, it has been shown that another HSP named Clusterin can act simultaneously as a tumor suppressor and a tumor promoter depending on the stage of cancer that is overexpressed." (PMID 36768927, 2023). "Downregulation of nCLU expression was found to enhance tumor formation, therefore leading to the conclusion that CLU might also be a tumor and metastasis suppressor gene." (PMID 37685987, 2023). "The Gene Expression Profiling Interactive Analysis (GEPIA), which relies on tumor tissues from The Cancer Genome Atlas (TCGA) and normal tissues from the Genotype-Tissue Expression (GTEx) project, unveiled that the expression patterns of CLU exhibited tumor specificity." (PMID 37686218, 2023). "This suggests that clusterin may have both a cancer promoter and suppressor role, depending on the tumor type and specific context." (PMID 37834086, 2023).